NOX4 (NADPH oxidase 4)
Diseases named in the same sentence as NOX4 in open-access papers (continued):
Sharing a sentence is not in itself a finding about the gene and the disease.
pneumonia (4 papers, 2022 to 2025). An acute, acute and chronic, or chronic inflammation focally or diffusely affecting the lung parenchyma, caused by an infection in one or both of the lungs (by bacteria, viruses, fungi, or mycoplasma.). "Using PCR-DNA sequence verdicts, the IL-1α (356-bp), IL-1β (423-bp), IL-6 (384-bp), TNFα (490-bp), IL-10 (306-bp), IFN-γ (321-bp), PRDX6 (434-bp), ATG7 (416-bp), NDUFS6 (405-bp), and NOX4 (396-bp) genes were found to have different SNPs in the amplified DNA bases linked to pneumonia." (PMID 40711280, 2025). "Our investigation used a PCR-DNA-sequencing procedure to illustrate the difference in immunological (IL-1α, IL1B, IL6, TNF-α, IL10, and IFN-γ) and antioxidant (PRDX6, ATG7, NDUFS6, and NOX4) genes in calves with pneumonia and healthy calves." (PMID 40711280, 2025). "The genes IL-1α, IL1B, IL6, TNF-α, IL10, IFN-γ, and NOX4 had significantly greater gene expression levels in pneumonia-affected calves compared to the CON group." (PMID 40711280, 2025). "NOX4 and EphA2 levels were significantly higher in patients with pneumonia and especially in mechanical ventilated in the ICU." (PMID 35346198, 2022). "Among the pneumonia patients, NOX4 levels were highest in the group that received mechanical ventilator care (p < 0.01 compared with that in the control group, and p < 0.05 compared with that in pneumonia patients without ventilation)." (PMID 35346198, 2022). "In particular, NOX4 levels were significantly higher in the group of pneumonia patients using ventilators in the ICU, matching the data derived from the mouse experiments." (PMID 35346198, 2022). "In patients with respiratory disease, NOX4 and EphA2 levels were significantly higher in patients with pneumonia and patients who received ventilator treatment in the intensive care unit." (PMID 35346198, 2022). "The NOX4 and EphA2 levels were significantly higher in patients with pneumonia compared with those in the control group." (PMID 35346198, 2022). "In our study, NOX4/EphsA2 levels in BALF were also high in patients with pneumonia." (PMID 35346198, 2022). "The inhibition of PKC or NOX4 attenuated Pseudomonas aeruginosa-induced lung inflammatory injury by inhibiting ROS production and LPS-induced ALI by inhibiting apoptosis and secretion of proinflammatory cytokines in pneumonia cells." (PMID 36959535, 2023). "In addition, the relationship between EphA2 (which is related to lung injury) and NOX4 was investigated using EphA2 KO mice, and NOX4 and EphA2 levels in the bronchoalveolar lavage fluid (BALF) of 38 patients with pneumonia were examined." (PMID 35346198, 2022). "The NOX4 and EphA2 levels in BALF were investigated in patients with/without pneumonia." (PMID 35346198, 2022).
alcoholic liver diseases (3 papers, 2017 to 2026). A disorder caused by damage to the liver parenchyma due to alcohol consumption. "In a mouse model of alcoholic liver disease, HuR was found to play a key role in NOX4 mediated increase in CCL2 mRNA stability." (PMID 37961304, 2025).
allergic asthma (3 papers, 2024). A asthma with a basis in a pathological type I hypersensitivity reaction. "Kaempferol can inhibit airway inflammation and airway remodeling by interfering with signal transduction in mast cells and recombinant nicotinamide adenine dinucleotide phosphate oxidase 4 (NOX4)-mediated autophagy, effectively improving allergic asthma symptoms in guinea pigs." (PMID 38590639, 2024). "This study has found that kaempferol binds NOX4 to perform its functions in the treatment of allergic asthma, which could potentially provide an effective therapeutic strategy for the further treatment of asthma." (PMID 38731498, 2024). "A study on allergic asthma reported that, in the TGF-β1-induced human bronchial epithelial cells (BEAS-2B), the NOX4 expression was reduced with a kaempferol dose increase." (PMID 38731498, 2024).
aortic stenosis (3 papers, 2023 to 2025). Aortic valve stenosis is a aortic valve disease caused by the incomplete opening of the aortic valve. "Aerobic exercise training also reduced the gene expression of the subunit p22phox, required for both NOX2 and NOX4 activation, in aortic stenosis animals." (PMID 37362442, 2023). "Alterations in gene expression of sources that generate reactive species of oxygen were observed in AS-Ex group, which showed decreased mRNA abundance of NOX2 and NOX4 compared to the aortic stenosis group (p < 0.05)." (PMID 37362442, 2023). "Aortic stenosis increased Nox4 gene expression compared to control group, which was reduced by aerobic exercise." (PMID 37362442, 2023).
bone cancer (3 papers, 2022 to 2024). A primary or metastatic malignant neoplasm affecting the bone or articular cartilage. "Furthermore, in a model of cancer-induced bone pain, Nox4 expression was induced in spinal microglia, and the downregulation of Nox4 by intrathecal lentiviral injection attenuated bone-cancer-induced pain behavior." (PMID 35740059, 2022). "Finally, the result is that the downregulation of NOX4 inhibits GABAA-γ2 and NMDAR expression in the SDH to alleviate bone cancer pain, compensating for the contribution of NOX4 to central sensitization." (PMID 37921169, 2024).
breast tumors (3 papers, 2022 to 2024). "The same authors also showed that NOX4 was overexpressed in various BC cell lines and primary breast tumors." (PMID 38542437, 2024). "More importantly, we found a significant upregulation of Nox4 expression in CAFs isolated from human breast tumors versus normal mammary fibroblasts (RMFs)." (PMID 35836253, 2022). "To further show the clinical significance of Nox4, we determined Nox4 transcription levels in a panel breast tumor microarray (TMA)." (PMID 35836253, 2022).
cholestasis (3 papers, 2016 to 2020). Impairment of the bile flow caused by obstruction within the liver, or outside the liver in the bile duct system. "The present study found that the protein level of NADPH oxidase 4 (NOX4) in placenta was significantly increased in pregnant mice of E2-induced cholestasis." (PMID 31827696, 2019). "From a mechanistic perspective, we previously proved that paeoniflorin, the main active component of PLP, displayed its effect on cholestasis by reducing the production of ROS and NOX4." (PMID 26869930, 2016). "Moreover, paeoniflorin also alleviates cholestasis through an antioxidative mechanism by downregulating ROS and NOX4 and upregulating the PI3K/Akt/Nrf2 pathway." (PMID 32410996, 2020). "Moreover, OCA inhibited the upregulation of placental NADPH oxidase-4 and antioxidant genes during cholestasis." (PMID 31827696, 2019).
colon adenocarcinoma (3 papers, 2018 to 2025).
cyst (3 papers, 2017 to 2025). A sac-like closed membranous structure that may be empty or contain fluid or amorphous material. "Additionally, Nox4-deficient mice showed increased susceptibility to virulent RH strain infection and increased cyst burden in brain tissues and low levels of MIF expression following infection with the avirulent ME49 strain." (PMID 28743960, 2017). "Importantly, increased NOX4 was not limited to cyst-lining TECs and was present also in non-cystic tubules, suggesting that NOX4 is an important early modulator of cellular ROS." (PMID 32183375, 2020). "Interestingly, NOX4 immunoreactivity increased not only in cyst-lining cells but also in non-cystic tubules." (PMID 32183375, 2020).
dementia (3 papers, 2019 to 2025). Loss of intellectual abilities interfering with an individual's social and occupational functions. "For example, a recent systematic review of single-cell studies in dementia highlights that endothelial and other vascular-associated cell types show transcriptional alterations in AD and other dementias, supporting the feasibility of examining NOX4 expression in clinical vascular datasets." (PMID 40725005, 2025).
dilated cardiomyopathy (3 papers, 2020 to 2025). Cardiomyopathy which is characterized by dilation and contractile dysfunction of the left and right ventricles. "In Elmo1-hypermorphic mice, systemic NOX4 deletion alleviates the dilated cardiomyopathy phenotype, restores cardiac morphology and LV contractile function." (PMID 41009041, 2025). "Studies also suggest that NOX4 upregulation increases pyroptosis, and NOX4 inhibition attenuates pytoptosis in mice with dilated cardiomyopathy." (PMID 33584299, 2020). "In dilated cardiomyopathy, Drp1 induced constitutive expression of NOX1 and NOX4 while promoted NLRP3 inflammasome activation through mitochondrial fission." (PMID 35711428, 2022).
disc degeneration (3 papers, 2020 to 2023). "Discs with blocked NOX4 expression had lower grades of degeneration and down-regulated expression of senescence markers and senescence-associated inflammatory proteins, suggesting an important role for NOX4 in disc degeneration caused by AOPPs." (PMID 35935259, 2022). "In summary, both EZH2 and NOX4 are involved in natural disc degeneration." (PMID 32025238, 2020). "Our experimental results show that blocking the high expression of NOX4 could block most of the downstream pathological effects induced by AOPPs, thus this positive feedback loop can be blocked, oxidative stress can be controlled, and the rate of disc degeneration can be slowed down." (PMID 35935259, 2022). "EZH2 and NOX4 are jointly involved in the regulation of aging of NP cells which provide a new idea for further research on the mechanism of disc degeneration, potential targets for early clinical diagnosis and treatment of IDD." (PMID 32025238, 2020).
gastric adenocarcinoma (3 papers, 2022 to 2025). "NOX4 (NADPH oxidase 4) is an enzyme that generates reactive oxygen species and is overexpressed in gastric adenocarcinoma." (PMID 38752750, 2024). "RT-qPCR results indicated that the mRNA expression levels of four hypoxic endoplasmic reticulum stress-related differential genes—NOX4, ANGPT2, CD36, and TLR2—were correlated with our established prognostic risk model in both gastric adenocarcinoma and adjacent normal tissues." (PMID 40061897, 2025). "NOX4 expression showed a downward trend in gastric adenocarcinoma, although this was not statistically significant." (PMID 40061897, 2025).
gastric tumor (3 papers, 2022 to 2024). "Analysis of gastric tumors has correlated NOX2 overexpression with longer patient survival, in contrast with NOX4 overexpression, which is associated with poorer overall patient survival." (PMID 38542437, 2024). "We found that compared with those in normal samples, gastric tumor samples had significantly increased TNF, NOX4, and LONP1 mRNA levels and decreased DUSP1 mRNA levels." (PMID 38758860, 2024).
Hashimoto thyroiditis (3 papers, 2013 to 2023). An autoimmune disorder caused by the production of autoantibodies against thyroid tissue. "In contrast to GD, in Hashimoto’s thyroiditis, Th1 cytokines appear to directly upregulate NOX4 and ROS production." (PMID 35008579, 2021).
head and neck cancer (3 papers, 2017 to 2021). A primary or metastatic malignant neoplasm affecting the head and neck. "Erlotinib, by inhibiting EGFR, induces metabolic oxidative stress through NOX4 in human head and neck cancer cells." (PMID 33920356, 2021). "NOX4-induced autophagy was reported to trigger anticancer drug resistance in head and neck cancer." (PMID 33567693, 2021). "Indeed, the increased expression of NOX4 has been found to be responsible for superoxide formation under erlotinib treatment in human head and neck cancer (HNSCC) cells." (PMID 28915658, 2017).
hematoma (3 papers, 2020 to 2025). A hematoma is a collection of blood from a vascular structure into an extravascular space. "Then antagomiR‐25 further upregulated the expression of Nox4, promoted the level of oxidative stress, increased hematoma volume, exacerbated brain edema and neurological deficits, whereas agomiR‐25 reversed the effects promoted by KIRA6." (PMID 37994671, 2024).
hyperuricemia (3 papers, 2017 to 2022). An abnormally high level of uric acid. "Meanwhile, we evaluate the change of NADPH oxidase 4 (Nox4), which expressed abundantly in renal proximal tubule, and fount it upregulated in hyperuricemia mice while downregulated by baicalein." (PMID 28445133, 2017).
influenza (3 papers, 2020 to 2022). An acute viral infection of the respiratory tract, occurring in isolated cases, in epidemics, or in pandemics; it is caused by serologically different strains of viruses (influenzaviruses) designated A, B, and C, has a 3-day incubation period, and usually lasts for 3 to 10 days. "We have investigated viral pathogenesis in the endothelial NOX4 overexpressing mouse [2-3 fold increase in endothelial NOX4 expression] and WT control mice to examine the differential effect of NOX4 expression on influenza pathogenesis." (PMID 35601109, 2022). "The aim of this study was to determine if endothelial NOX4 expression can influence viral pathology in vivo, using a mouse model of influenza infection." (PMID 35601109, 2022). "While there have been several studies examining the role of NOX4 in inflammatory pathways in the setting of cardiovascular disease, there has been limited investigation of the role of NOX4 in influenza pathology." (PMID 35601109, 2022). "Influenza infected NOX4 TG mice had decreased expression of CXCL10, CCL3, CXCL1 and CXCL2 three days post infection." (PMID 35601109, 2022). "The decrease in CXCL10 expression in the influenza-infected NOX4 TG mice compared to infected WT mice is consistent with both the decrease in neutrophil infiltration and the decrease in lung weight seen in infected NOX4 TG mice." (PMID 35601109, 2022). "It is also reported that influenza infection significantly increases ROS production by inducing Nox4, and the proliferation of this virus in lung epithelial cells is dependent on redox-sensitive pathways activated by Nox4-derived ROS." (PMID 32161622, 2020). "NOX4 is the most abundantly expressed isoform of the NOX enzyme family in lung endothelial cells and the expression of this, ROS producing enzyme was specifically suppressed in response to influenza infection." (PMID 35601109, 2022). "Previous studies have indicated that flavonoids can inhibit influenza and attenuate H1N1-induced acute lung injury, probably via inhibiting TLR signaling, suppressing NOX4/NF-κB/MLCK pathway, and inhibiting influenza H1N1 virus neuraminidase." (PMID 35677448, 2022). "CCL3 and CXCL10 are known to trigger the infiltration of macrophages in influenza infection yet, despite the decrease in these chemokines, there was no change in the number of macrophages in the infected NOX4 TG." (PMID 35601109, 2022). "The complexity of cancer cell ROS biology could have a confounding effect on the conclusions from this initial viral study and there have been no in vivo studies examining the effect of endothelial NOX4 on influenza pathology in an animal model of pathogenesis." (PMID 35601109, 2022).
ischemia reperfusion injury (3 papers, 2022 to 2025). Adverse functional, metabolic, or structural changes in ischemic tissues resulting from the restoration of blood flow to the tissue (reperfusion), including swelling; hemorrhage; necrosis; and damage from free radicals. "While NOX isoforms are primarily associated with the plasma membrane, there is evidence suggesting that NOX4 present in the mitochondria, has been implicated in the pathogenesis of ischemia-reperfusion injury." (PMID 38061207, 2024). "AKI caused by ischemia–reperfusion injury can induce a significant increase in lysine-specific demethylase 1 expression through the AKT pathway, thereby affecting the lysine metabolic pathway and generating oxidative stress and ferroptosis via the TLR4/NOX4 pathway." (PMID 41189893, 2025).
keloid (3 papers, 2022 to 2024). An irregularly shaped, elevated mark on the skin caused by deposits of excessive amounts of collagen during wound healing. "Epidermal keratinocytes from keloids showed an evident overexpression of NOX4 that was also reproduced with lower intensity in epidermal keratinocytes from hypertrophic scars as observed in immunofluorescence and RT-PCR for NOX4." (PMID 39223490, 2024). "In this present study, innovatively combining SVM-RFE and LASSO-logistic regression methods, we identified four biomarkers (STC2, SDC4, DAAM1, and NOX4) for keloid and further explored the role of ICI on keloid." (PMID 35719372, 2022). "Here, we observed for the first time that keloid epidermis and in a lesser extent hypertrophic scar epidermis express large amounts of NOX4, and that TGFβ1 induces the expression of NOX4 and reactive oxygen species which is inhibited by roflumilast and siRNA-PDE4B." (PMID 39223490, 2024). "During keloid formation, EGR1 responds to TGF-β and promotes ROS production by activating NADPH oxidase 4 (NOX4)." (PMID 38943627, 2024). "Compared to normal group, the relative expression levels of SDC4, NOX4, DAMM1, and STC2 in keloid fibroblasts were 0.28 ± 0.13, 2.07 ± 0.32, 2.11 ± 0.63, and 1.87 ± 1.56, respectively." (PMID 35719372, 2022). "In addition, we also conducting a qRT-PCR experiment for detecting differential expression of SDC4, NOX4, DAMM1, and STC2 between keloid and normal tissue." (PMID 35719372, 2022).
lung adenocarcinoma (3 papers, 2018 to 2024). A carcinoma that arises from the lung and is characterized by the presence of malignant glandular epithelial cells. "By targeting NOX4, miR-99a reduced NOX4 levels and also migration and invasion in lung adenocarcinoma and inhibited xenograft growth." (PMID 34199590, 2021).
metastatic melanoma (3 papers, 2016 to 2023). A melanoma that has spread from its primary site to another anatomic site. "Collectively, these data suggest a role of eNOS, NOX1 and NOX4 in metastatic melanoma." (PMID 27756874, 2016). "In melanocytic lineages, Nox1, Nox4, and Nox5 are expressed; Nox4 expression is significantly higher in a subset of metastatic melanoma tumors, while in primary and metastatic melanoma tissues, Nox1 is not differentially expressed." (PMID 37189846, 2023). "However, we noticed a huge expression of both c-met and Nox4 in metastatic melanoma, unlike in cases without recurrences." (PMID 33451139, 2021).
nonalcoholic steatohepatitis (3 papers, 2020 to 2023). "TGF-β-induced NOX4 regulates oxidative stress in the liver and levels of TGF-β ligands and NOX4 are increased in fibrotic patients, both virus- and non-alcoholic steatohepatitis (NASH)-related, as well as in mice with diet-induced steatohepatitis." (PMID 34571961, 2021).
oral carcinoma (3 papers, 2019 to 2023). "Studies have shown that miR-99a-5p acts as a tumour suppressor and exerts inhibitory effects in several tumour cells, such as in human oral lymphoid carcinoma cells TSCC1, and miR-99a-5p can affect the proliferation, migration and invasion of human oral cancer cells by inhibiting NOX4 expression." (PMID 37081566, 2023). "Furthermore, it has been suggested that the downregulation of miR-99a-5p promotes cancer progression in human oral carcinoma cells, signaling via NOX4." (PMID 30621620, 2019).